FUS (FUS RNA binding protein)
Description:
DNA/RNA-binding protein that plays a role in various cellular processes such as transcription regulation, RNA splicing, RNA transport, DNA repair and damage response. Binds to ssRNA containing the consensus sequence 5'-AGGUAA-3'. Binds to nascent pre-mRNAs and acts as a molecular mediator between RNA polymerase II and U1 small nuclear ribonucleoprotein thereby coupling transcription and splicing. Also binds its own pre-mRNA and autoregulates its expression; this autoregulation mechanism is mediated by non-sense-mediated decay. Plays a role in DNA repair mechanisms by promoting D-loop formation and homologous recombination during DNA double-strand break repair. In neuronal cells, plays crucial roles in dendritic spine formation and stability, RNA transport, mRNA stability and synaptic homeostasis (By similarity).
Synonyms: TLS; FUS1; hnRNP-P2; HNRNPP2; ALS6; ETM4; POMP75; altFUS
Tractability: Small molecule: a structure with a bound ligand is known. PROTAC: UniProt records ubiquitination sites on it; ubiquitination databases record sites on it; its protein half-life has been measured.
Gene: Protein-coding gene on chromosome 16 (31,180,134 to 31,196,963, forward strand). Ensembl gene ENSG00000089280.
Subcellular location: Nucleus
Subcellular location (Human Protein Atlas): Nucleoplasm
Pathways (Reactome):
Metabolism of RNA: Processing of Capped Intron-Containing Pre-mRNA; mRNA Polyadenylation; mRNA Splicing - Major Pathway
Disease: Dengue Virus-Host Interactions
Gene Ontology:
Molecular function: chromatin binding; identical protein binding; molecular condensate scaffold activity; protein binding; RNA binding; transcription coactivator activity; transcription coregulator activity; mRNA 3'-UTR binding; nucleic acid binding
Biological process: amyloid fibril formation; membraneless organelle assembly; mRNA stabilization; positive regulation of double-strand break repair via homologous recombination; protein homooligomerization; regulation of DNA-templated transcription; regulation of RNA splicing; regulation of transcription by RNA polymerase II; RNA splicing; positive regulation of DNA-templated transcription
Cellular component: nucleoplasm; nucleus; cytoplasm; GABA-ergic synapse; glutamatergic synapse; postsynaptic cytosol; presynaptic cytosol
Genetic constraint (gnomAD): Loss-of-function variants: 3 observed, 74.81 expected, observed/expected ratio (o/e) 0.0401, 90% interval 0.017 to 0.1. The upper end of that interval is the gene's LOEUF score, 0.1, which puts it in group 1 of 6, group 1 being the genes least tolerant of losing a copy. Missense variants: 477 observed, 679.3 expected, observed/expected ratio (o/e) 0.7, 90% interval 0.65 to 0.76. Synonymous variants: 254 observed, 237.42 expected, observed/expected ratio (o/e) 1.07, 90% interval 0.96 to 1.19.
Gene-disease validity (ClinGen):
ClinGen rates the evidence that FUS causes each of these diseases.
amyotrophic lateral sclerosis type 6 (autosomal dominant): Definitive.
Cancer hallmarks: invasion and metastasis (suppresses); suppression of growth (promotes)
Homologues: Orthologues: chimpanzee FUS (99% identical), macaque TRIM72 (96% identical), mouse Fus (96% identical), rat Fus (94% identical), dog FUS (94% identical), rabbit FUS (94% identical), pig FUS (94% identical), guinea pig FUS (89% identical), tropical clawed frog fus (75% identical), zebrafish fus (66% identical), Caenorhabditis elegans fust-1 (34% identical), Drosophila melanogaster caz (27% identical). Paralogues in human: EWSR1 (56% identical), TAF15 (45% identical).
Diseases named in the same sentence as FUS in open-access papers:
FUS is named in the same sentence as 231 diseases in open-access papers, as found by Europe PMC text mining. Sharing a sentence is not in itself a finding about the gene and the disease. The quoted sentences say what the papers report.
amyotrophic lateral sclerosis (463 papers, 2009 to 2026). Amyotrophic lateral sclerosis (ALS) is a neurodegenerative disease characterized by progressive muscular paralysis reflecting degeneration of motor neurons in the primary motor cortex, corticospinal tracts, brainstem and spinal cord. "In animals, lipoamide ameliorates aging-associated aggregation of a stress granule reporter protein, improves neuronal morphology and recovers motor defects caused by amyotrophic lateral sclerosis-associated FUS and TDP-43 mutants." (PMID 40369342, 2025). "In another instance, DeepMVP predicted that the R524S variant in the RNA-binding protein FUS, a variant associated with amyotrophic lateral sclerosis (ALS), would be associated with enhanced phosphorylation at Y526 (delta score, 0.70)." (PMID 40859022, 2025). "Genetic testing confirmed juvenile-onset amyotrophic lateral sclerosis due to a pathogenic FUS gene mutation (p.Pro525Leu)." (PMID 41164053, 2025). "Mutations and aberrant phase behavior of FUS are linked to neurodegenerative disorders such as amyotrophic lateral sclerosis (ALS) and frontotemporal dementia (FTD), where abnormal condensate dynamics and aggregation contribute to disease progression." (PMID 40667293, 2025). "In 2009, mutations in the fused in sarcoma/translocated in sarcoma (FUS) gene were identified as a cause of amyotrophic lateral sclerosis (FUS-ALS)." (PMID 40659544, 2025). "The RNA and DNA-binding protein Fused in Sarcoma (FUS), linked to amyotrophic lateral sclerosis (ALS), functions in multiple RNA processes in neuronal cell nuclei." (PMID 39149613, 2024). "For example, TAR DNA-binding protein 43 (TDP-43) and fused in sarcoma (FUS), which are associated with amyotrophic lateral sclerosis, are DNA/RNA-binding proteins that contain nuclear localization sequences (NLS)." (PMID 37047616, 2023). "We observed a similar direction of changes in rRNA modification in differentiated SH-SY5Y cells with the FUS mutation (R495X) related to the severe disease phenotype of amyotrophic lateral sclerosis (ALS)." (PMID 36806717, 2023). "In particular, numerous FUS mutations have been found in familial forms of amyotrophic lateral sclerosis (ALS) and frontotemporal lobar degeneration (FTLD), indicating an essential role for this protein in neurodegenerative diseases." (PMID 36806717, 2023). "In particular, some mutations of FUS (FUsed in Sarcoma) protein are related to amyotrophic lateral sclerosis (ALS)." (PMID 38086853, 2023). "Aberrant aggregation of FUS is implicated in various neurodegenerative diseases, such as amyotrophic lateral sclerosis, frontotemporal dementia, and so on." (PMID 36990219, 2023). "We additionally engineered a Css DNA construct that encodes the ALS (amyotrophic lateral sclerosis)-related protein FUS (fused in sarcoma), which was tagged with a red fluorescent protein (RFP)." (PMID 37863879, 2023). "This echoes previous findings in a fly model, showing that the amyotrophic lateral sclerosis and frontotemporal lobar degeneration‐associated FUS protein can be transported to mitochondria via HSP60, thereby inducing mitochondrial impairment and cell death." (PMID 35373908, 2022). "For instance, mutations found in the fused in sarcoma (FUS) protein of amyotrophic lateral sclerosis (ALS) patients, significantly increase the rate and strength of its gelation." (PMID 36175408, 2022). "For instance, aggregated FUS mutants associated with amyotrophic lateral sclerosis sequester the histone methyltransferase PRMT1 to the cytoplasm, leading to a decrease in the levels of asymmetric H4R3me2." (PMID 36558770, 2022). "This is in line with a previous report investigating an SVA element inserted upstream of the FUS gene and is thus associated with amyotrophic lateral sclerosis and frontotemporal dementia." (PMID 35216353, 2022). "The CR18854 gene also shows a genetic interaction with Cabeza (dFUS), a Drosophila homolog of human FUS and one of the causing genes of amyotrophic lateral sclerosis (ALS)." (PMID 36675966, 2022).
amyotrophic lateral sclerosis (continued). "For instance, TDP-43 and FUS, which are both mutated in amyotrophic lateral sclerosis (ALS), control the axonal localization of mRNAs." (PMID 35220080, 2022). "Fused in sarcoma (FUS) is an RNA-binding protein that is genetically and pathologically associated with rare and aggressive forms of amyotrophic lateral sclerosis (ALS) and frontotemporal dementia (FTD)." (PMID 35075293, 2022). "FUS mutations in patients with amyotrophic lateral sclerosis (ALS) cause protein inclusion and sequester translation, thereby affecting NMD." (PMID 36142288, 2022). "In motoneurones carrying FUS mutation, a condition linked to amyotrophic lateral sclerosis (ALS), the same stimulus results in the great segregation of circ-Hdgfrp3 into cytoplasmic mutant FUS assemblies." (PMID 36239357, 2022). "Mutations in the human DNA/RNA binding protein FUS are associated with amyotrophic lateral sclerosis and frontotemporal lobar degeneration, including some aggressive and juvenile onset forms." (PMID 34568776, 2021). "Mutations within this protein – which is known as FUS, short for Fused in sarcoma – can lead to the motor neuron disease known as amyotrophic lateral sclerosis (ALS)." (PMID 34636721, 2021). "Methylation of recombinant or purified FUS protein, the protein that phase separates into granules in amyotrophic lateral sclerosis (ALS) mutations, similarly reduces liquid-liquid de-mixing." (PMID 33898525, 2021). "While oncogenic fusions of FUS and transcription factor DNA-binding domains are associated with soft tissue sarcomas, dominant mutations in FUS can cause amyotrophic lateral sclerosis." (PMID 34375640, 2021). "Amyotrophic lateral sclerosis-linked FUS mutations clearly alter RNA metabolism, but this influence is not a one-way street." (PMID 34349625, 2021). "Mutations in the RNA-binding protein (RBP) FUS have been genetically associated with the motoneuron disease amyotrophic lateral sclerosis (ALS)." (PMID 34471224, 2021). "Mutations in Fused-in-Sarcoma (FUS) gene involving the nuclear localization signal (NLS) domain lead to juvenile-onset Amyotrophic Lateral Sclerosis (ALS)." (PMID 35002600, 2021). "FUS mutations lead to its cytoplasmic mislocalization and cause the neurodegenerative disease amyotrophic lateral sclerosis (ALS)." (PMID 34290090, 2021). "Mutations in the FUS gene first identified in patients with amyotrophic lateral sclerosis (ALS) lead to the accumulation of the FUS protein in cytoplasmic inclusions." (PMID 34088960, 2021). "Mutations in the fused in sarcoma (FUS) gene have been associated with amyotrophic lateral sclerosis (ALS), frontotemporal lobar degeneration, and essential tremor." (PMID 32307925, 2020). "Mutations in the RNA-binding protein FUS cause amyotrophic lateral sclerosis (ALS), a devastating neurodegenerative disease." (PMID 32479602, 2020). "On the other hand, FUS participates in DNA repair mechanisms and is frequently mutated in amyotrophic lateral sclerosis." (PMID 32175077, 2020). "SMN protein localizes in nuclear bodies that are lost in SMA and adult onset amyotrophic lateral sclerosis (ALS) patient cells harboring TDP-43 or FUS/TLS mutations." (PMID 32363199, 2020). "Mutations in the FUS gene are responsible for a subset of amyotrophic lateral sclerosis (ALS) cases referred to as ALS-FUS." (PMID 32404191, 2020). "Mutations in the RNA-binding protein Fused in Sarcoma (FUS) cause early-onset amyotrophic lateral sclerosis (ALS)." (PMID 33311468, 2020). "Mutations in RNA-binding proteins (RBPs) such as TAR DNA-binding protein 43 (TDP-43) and fused in sarcoma (FUS) are associated with amyotrophic lateral sclerosis (ALS) and frontotemporal dementia (FTD)." (PMID 32184412, 2020). "Mutations in TDP-43 and FUS have been identified in patients with the familial form of the neurodegenerative disorder amyotrophic lateral sclerosis (ALS), which is characterized by progressive loss of motoneurons and muscle atrophy." (PMID 32187190, 2020).
amyotrophic lateral sclerosis (continued). "FUS translocation events and mutations have been linked with liposarcoma and amyotrophic lateral sclerosis, respectively." (PMID 33128015, 2020). "Mutations in fused-in-sarcoma RNA-binding protein (FUS) and in heterogeneous nuclear ribonucleoprotein A1 (hnRNPA1) are involved in familial forms of amyotrophic lateral sclerosis (ALS) and frontotemporal dementia (FTD)." (PMID 33260713, 2020). "Mutations in fused in sarcoma (FUS) lead to amyotrophic lateral sclerosis (ALS) with varying ages of onset, progression and severity." (PMID 31811140, 2019). "The protein has been of medical interest because point mutations in FUS can cause neurodegenerative disorders such as amyotrophic lateral sclerosis (ALS) and frontotemporal dementia (FTD)." (PMID 31500099, 2019). "On the other hand, a large array of point mutations of the FUS protein were identified to cause neurodegenerative diseases, including Amyotrophic lateral sclerosis (ALS) and frontotemporal lobar dementia (FTLD)." (PMID 31188823, 2019). "The second dataset individually depleted three RBPs implicated in amyotrophic lateral sclerosis: FUS, TAF15 and TARDBP." (PMID 31238884, 2019). "Abnormal cytoplasmic accumulation of fused in sarcoma (FUS) protein is the pathological hallmark of some cases of amyotrophic lateral sclerosis (ALS) with transactive response DNA‐binding protein of 43KDa (TDP‐43)‐negative pathology that lack SOD1 mutations." (PMID 30375034, 2019). "Amyotrophic lateral sclerosis caused by mutations in the FUS gene is characterized by cytoplasmic FUS pathology (FUS proteinopathy)." (PMID 31875556, 2019). "FUS protein is also a pathological hallmark of neurodegenerative diseases such as amyotrophic lateral sclerosis and frontotemporal lobe degeneration." (PMID 30736838, 2019). "For example, CDR1as/CiRS-7 is dramatically reduced in sporadic Alzheimer’s disease and a group of circRNAs has been found to be regulated by the Fused in Sarcoma (FUS) RNA binding protein in an amyotrophic lateral sclerosis-associated cellular model." (PMID 30400273, 2018). "Here the authors investigate the mechanisms of defects in repair caused by mutations in the RNA/DNA binding protein FUS in amyotrophic lateral sclerosis and elucidate its role in the DNA ligation during DNA single-strand break repair of oxidative breaks." (PMID 30206235, 2018). "Mutations in proteins like FUS which cause Amyotrophic Lateral Sclerosis (ALS) result in the aberrant formation of stress granules while ALS-linked mutations in other proteins impede elimination of stress granules." (PMID 30022074, 2018). "FUS regulates several RNA metabolic processes, including RNA splicing, and is linked to the pathogenesis of amyotrophic lateral sclerosis (ALS) and frontotemporal dementia (FTD)." (PMID 29311805, 2017). "Mutations in FUS are causative for amyotrophic lateral sclerosis with a dominant mode of inheritance." (PMID 29053787, 2017). "Mutations in Fused in Sarcoma/Translocated in Liposarcoma (FUS) cause familial forms of amyotrophic lateral sclerosis (ALS), a neurodegenerative disease characterized by progressive axonal degeneration mainly affecting motor neurons." (PMID 28273913, 2017). "Mutations in FUS cause amyotrophic lateral sclerosis (ALS), including some of the most aggressive, juvenile-onset forms of the disease." (PMID 26842965, 2016). "Translocated in LipoSarcoma [TLS, also known as FUsed in Sarcoma (FUS)] is an RNA/DNA binding protein whose mutation causes amyotrophic lateral sclerosis (ALS)." (PMID 26816614, 2016). "FUS gene is well-known as related-gene of tumor of human myxoid liposarcoma and associated with amyotrophic lateral sclerosis." (PMID 27150598, 2016). "More recently, two mutants of FUS causing amyotrophic lateral sclerosis have shown different RNA-binding patterns compared to their wild-type counterparts, supporting the importance of the function of FUS in mRNA processing." (PMID 27812418, 2016).
amyotrophic lateral sclerosis (continued). "For proof of principle, conditional alleles were generated for cabeza (caz), the Drosophila homolog of human FUS, a gene implicated in the neurodegenerative disorders amyotrophic lateral sclerosis (ALS) and frontotemporal dementia (FTD)." (PMID 25772687, 2015). "Intriguingly, several of the mutations in the FUS gene identified in familial cases of amyotrophic lateral sclerosis (F-ALS) are located in the regions implicated in the interaction with HDAC1." (PMID 25926848, 2015). "FUS is an RNA/DNA-binding protein involved in multiple steps of gene expression and is associated with amyotrophic lateral sclerosis (ALS) and fronto-temporal lobar degeneration (FTLD)." (PMID 25968143, 2015). "FUS is an RNA/DNA-binding protein involved in gene expression regulation and associated with amyotrophic lateral sclerosis and frontotemporal dementia (FTLD) but the disease-causing mechanisms are unclear." (PMID 25968143, 2015). "Mutations in the FUS gene on chromosome 16, have been shown to be a rare cause of amyotrophic lateral sclerosis (ALS-FUS), being responsible for approximately 4 % of cases of familial ALS (fALS) and fewer than 1 % of sporadic cases." (PMID 26452761, 2015). "Genetic mutations of FUS have been linked to many diseases including Amyotrophic Lateral Sclerosis (ALS) and Frontotemporal Lobar Degeneration." (PMID 24608899, 2014). "Mutations in the gene encoding fused in sarcoma/translocated in liposarcoma (FUS/TLS or FUS), also known as the heterogeneous nuclear ribonucleoprotein (hnRNP) P2, are linked to inherited cases of amyotrophic lateral sclerosis (ALS)." (PMID 24090136, 2013). "Examples include SMN2 mutations, which induce motor neuron degeneration in spinal muscular atrophy, and mutations in the RNA-binding proteins TDP-43 and FUS, which induce amyotrophic lateral sclerosis." (PMID 23865419, 2013). "Mutations in the DNA/RNA binding proteins TDP-43 and FUS are associated with Amyotrophic Lateral Sclerosis and Frontotemporal Lobar Degeneration." (PMID 22363618, 2012). "TDP-43 and FUS are RNA-binding proteins involved in the regulation of diverse RNA-processing events and have been strongly implicated in neurodegenerative diseases such as amyotrophic lateral sclerosis (ALS) and frontotemporal dementia (FTD)." (PMID 41796799, 2026). "Additionally, we observed an impaired stress response and a defect in nucleocytoplasmic transport, especially affecting the amyotrophic lateral sclerosis (ALS) associated protein FUS." (PMID 40970514, 2025). "Overexpression of TDP-43 and mutations in FUS that lead to the formation of cytoplasmic aggregates, depleting the nucleus of functional protein, contributes to the neurodegenerative diseases amyotrophic lateral sclerosis (ALS) and frontotemporal dementia (FTD)." (PMID 40601718, 2025). "Further reinforcing the concept that prevention of FUS nuclear translocation has antifibrotic potential, patients affected by amyotrophic lateral sclerosis carrying mutations of FUS known to confer cytoplasmic gain of function have a decreased amount of collagen IV in skin, urine, and plasma." (PMID 38488009, 2024). "Fused-in sarcoma (FUS) gene mutations have been implicated in amyotrophic lateral sclerosis (ALS)." (PMID 37887305, 2023). "We report the first analysis comparing the interactomes of three FUS variants: homeostatic wildtype FUS (FUS WT), phosphomimetic FUS (FUS PM; a proxy for N-terminally phosphorylated FUS), and the toxic FUS proline 525 to leucine mutant (FUS P525L) that causes juvenile amyotrophic lateral sclerosis." (PMID 35709984, 2022). "For two specific SVA D elements upstream of PARK7 (involved in pathogenesis of Parkinson’s disease) and FUS (linked to multiple neuropathologies including amyotrophic lateral sclerosis), the ability of SVA sequence to regulate gene expression rate was confirmed experimentally." (PMID 35628657, 2022). "Mutations in FUS are responsible for amyotrophic lateral sclerosis (ALS)." (PMID 34859816, 2022).